TNFSF10 (TNF superfamily member 10)
Diseases named in the same sentence as TNFSF10 in open-access papers (continued):
Sharing a sentence is not in itself a finding about the gene and the disease.
tumor (continued). "TRAIL (TNFSF10) can bind to TRAIL receptors (TRAIL-Rs), such as TRAIL-R1 in humans and TRAIL-R2 in humans and mice, which carry death domains that can induce caspase-8-mediated apoptosis of TRAIL-R+ tumor cells." (PMID 31134055, 2019). "The higher expression of TNFSF10 and GZMB in CIKIL-2 may account for the greater tumor cytotoxic efficiency of CIKIL-2 than CIKIL-15." (PMID 25826780, 2015). "Tumor NK cells downregulated canonical NK activation markers, such as FASLG, TNFSF10, KLRK1, GZMB, and KLRD1, the latter having both inhibitory and activator capabilities but being a marker of favorable prognosis in human cancers if present in either the serum or tumor." (PMID 41208961, 2025). "The TNF family-related transcripts TNFSF10 (encoding TRAIL, also known as APO-2 ligand) were also highly expressed by ILC2_c1 and ILC2_c2 subsets, acting as a cytotoxic protein which activates rapid apoptosis in tumor cells, but not in normal cells." (PMID 36960063, 2023). "Tumour cells are killed by CTLs, NK, NKT, γδT cells and macrophages, mechanisms including apoptosis inducing molecules ((Fas cell surface death receptor ligand(FASLG), TNF superfamily member 10 (TNFSF10)) and cytolytic molecules (granzyme, reactive oxygen species [ROS])." (PMID 35445563, 2022). "The tumor necrosis factor (ligand) superfamily, member 10 (TNFSF10) (TRAIL), upregulated 7.92-fold in HEC-1B cells with low DSCAM-AS1 levels, cells, has been reported to preferentially induce apoptosis or necroptosis in transformed and tumor cells and to decrease cancer cell growth." (PMID 35885035, 2022). "Of these seven, six genes—ECT2, NCEH1, TNFSF10, FNDC3B, GHSR, and SEMA6D—have either been observed at elevated expressions in tumor cells or have been documented acting as oncogenes for specific cancers in humans (genes that can transform cells into tumor cells)." (PMID 33767816, 2021). "Moreover, studies performed on TRAIL knockout mice show that TNFSF10 has an important role in normal tumour immunosurveillance as TNFSF10 knockout mice support tumour growth at a higher rate when compared with normal mice and are more susceptible to tumour metastasis." (PMID 20588276, 2010). "Tumor necrosis factor-related apoptosis-inducing ligand (TRAIL/TNFSF10), which was shown to induce apoptosis in many tumor cells but not in normal cells, is downregulated in CML patients, particularly in more advanced phases of the disease." (PMID 35057108, 2022). "Endogenous TNFSF10 (TRAIL), a member of the TNF family of ligands, selectively induces apoptosis of a variety of tumor cells without harming normal, non-transformed cells." (PMID 28686677, 2017). "Therefore, TNFSF10 may not be a contributor of enhanced tumor toxic function of CIKIL-2." (PMID 25108500, 2014). "TNFSF10 and BCL2L1 were other selected genes that were considered expression-driven dependency genes 4, and TNFSF10 belonged to the family of tumor necrosis factor (TNF) ligands that could induce apoptosis in tumor cells but normally did not kill healthy cells." (PMID 33850477, 2021).
cancer (1,831 papers, 2003 to 2026). A tumor composed of atypical neoplastic, often pleomorphic cells that invade other tissues. "TNFSF10 is associated with some human cancer types including ovarian cancer." (PMID 29170526, 2017). "Consistently, the expression of CDKN1C and KIT was lower in cancers, including KIRC, KIRP, and BRCA, while ICAM1, SSX2IP, and TNFSF10 were higher in cancers, including STAD and CESC, opposing the effects of miR-221/222-3p." (PMID 41602427, 2026). "TNFSF10, also known as TRAIL (TNF-related apoptosis-inducing ligand), encodes a member of the TNF superfamily that can selectively induce apoptosis in cancer cells upon binding to its receptors." (PMID 41295982, 2026). "We identified multiple TNF superfamily members with direct apoptotic effects on cancer cells, including TNFSF10 (TRAIL), TNFSF14 (LIGHT), TNFSF15 (TL1A), and LTA." (PMID 40564222, 2025). "TNFSF10 was mainly expressed in Tissue stem cells clusters of cancer tissues while generally expressed low in the cell clusters of paraneoplastic tissue." (PMID 38375157, 2024). "KRAS-positive tissues revealed weakly significant upregulation of BLNK and downregulation of MICB and TNFSF10 expression when compared to KRAS-negative cancer tissue." (PMID 37869102, 2023). "The products of TNF and TNFSF10 can be inhibited by binding to decoy receptors such as cFLIP, which are overexpressed in several cancer types and aid cell proliferation, growth and survival." (PMID 36679328, 2023). "There was a correlation between RNA-seq and validation cohort for the IL6R, BLNK, and TNFSF10 DEGs when cancer and control tissues were compared." (PMID 37869102, 2023). "TNFSF10 is also intimately involved in anti-cancer surveillance through immune cells, which is consistent with our results." (PMID 37670976, 2023). "TNF and TNFSF10 (TRAIL) secreted by M1-like and M2-like macrophages interact with their receptors expressed on cancer cells." (PMID 34793335, 2022). "Tumor necrosis factor (TNF)-related apoptosis-inducing ligand (TRAIL), also known as APO-2 ligand and TNFSF10, is a promising anti-cancer agent that belongs to the TNF superfamily." (PMID 28209994, 2017). "The data showed that inhibition of miR-7641 upregulated RPS16 in all cancer cell lines, while TNFSF10, RNF4, EMC8 and CUL3 responded irregularly." (PMID 28827731, 2017). "MDR1A KO tumors showed increased gene expression of TNFSF10 (TRAIL), a known inducer of cancer cell death, and CCL12, a strong trigger of B cell chemotaxis." (PMID 28686677, 2017). "TNFSF10/TRAIL (tumor necrosis factor [ligand] superfamily, member 10) induces cell death in different cancer cells and therefore contributes to immune cell-mediated cytotoxicity." (PMID 26222012, 2016). "Using filtering for genes involved in stem cell pluripotency, drug resistance, signal transduction and cancer, a few genes recurrently affected by genomic variations were identified, including TNFSF10 and FOXO3." (PMID 25593988, 2014). "TNFSF10 can induce apoptosis in several cancer cell lines with minimal toxicity against normal cells." (PMID 25050621, 2014). "In addition, this study found that DEGs in the three groups were also enriched in cancer and certain disease pathways (TNFSF10, ACKR4, FLT3, SIGLEC1, etc.)." (PMID 40282783, 2025). "TNFSF10 and its corresponding death receptor signaling can also regulate cancer metastasis." (PMID 38375157, 2024). "Interestingly, TNFSF10 expression in many cancers was consistently lower in African Americans compared with European Americans." (PMID 35930348, 2023). "Interferon-γ could upregulate the expression of TNFSF10 in T cells, NK cells, and DCs, which could induce the death of numerous carcinoma cells." (PMID 35174161, 2021). "TNFSF10 influences T cells function, which cannot only enhance the maximal suppressive function of Treg cells leading to the antitumor effect but also be involved in T cell-mediated killing of cancer cells." (PMID 31531018, 2019).
cancer (continued). "TNFSF10 induces apoptotic cell death in cancer by binding to its functional death receptors." (PMID 26580217, 2015). "Both CXCL10 and TNFSF10 have been shown to drive numerous human cancers into senescence." (PMID 23853104, 2013). "Unfortunately, the genome-wide association studies (GWAS) database used for the current study did not include apoptosis-related sequence variants (e.g., TNF-308 rs1800629, TNFSF10 rs1131532, BCL2 -936 rs2279115) previously reported in published cancer epidemiology studies." (PMID 22546513, 2012). "The HFDs also affected the expression of cancer-related genes in the proximal colon (and other parts of the intestines) including Vnn1 (vanin 1), a pantetheinase with roles in oxidative stress and inflammation 35, and Tnfsf10 (tumor necrosis factor ligand superfamily, member 10)." (PMID 37886485, 2023). "If we infer LR interactions on the basis of correlation, then the ligand TNFSF10 secreted from the malignant cell interacts with the receptor TNFRSF10B on malignant and fibroblast cells (circled in green), indicating likely apoptosis of malignant cells and cancer-associated fibroblasts (left)." (PMID 35302849, 2022). "TNFSF10/TRAIL could induce autophagy in certain cancer cells." (PMID 35743294, 2022). "TNFSF10, as a potential anti-cancer therapeutic agent, could inhibit cell growth and enhances cell apoptosis via binding to specific type I transmembrane death receptors, thereby assisting in the efficacy of the chemotherapy treatment of various cancers." (PMID 34356656, 2021). "In contrast, Cycling GZMA CD4 T cells expressed GZMA and demonstrated a marked upregulation of anti-cancer-related genes, including IFNG, PRF1, and TNFSF10." (PMID 40959273, 2025). "High fold change correlation for IL6R, TNFSF10, and BLNK DEGs was found between the matching samples and all CRC tissue samples in cancer vs. control correlation." (PMID 37869102, 2023). "TNFSF10, the superfamily member 10 of tumor necrosis factor (TNF), acts in an antitumor capacity by inducing cancer cell apoptosis while interacting with the corresponding receptor." (PMID 35755810, 2022). "Integrations occurred in the known cancer driver genes CCNA2, (four cases), TERT (one case), CCNE1 (three cases), TNFSF10 (two cases) and KMT2B (one case), leading to overexpression of the target genes." (PMID 36316711, 2022). "The tumour necrosis factor related apoptosis-inducing ligand (TRAIL), also known as Apo2L, CD253 or TNFSF10, can induce apoptosis in cancer cells while sparing normal cells." (PMID 31010082, 2019). "We further investigated the expression of alternative genes through which T cells can induce cytolysis of cancer cells, including CD95-CD95L (FAS-FASLG) and TRAIL-TRAILR (TNFSF10, TNFRSF10A/B)." (PMID 29515971, 2018). "TNFSF10 (tumor necrosis factor ligand super family member 10), also known as TRAIL, is a member of the TNF superfamily that induces apoptosis in various cancers by activating death receptors." (PMID 29849953, 2018). "Tumor necrosis factor-related apoptosis-inducing ligand (TRAIL, TNFSF10), a member of the TNF cytokine family, is an emerging therapeutic option for various cancers." (PMID 25527049, 2014). "The LCM data set shows significant over-expression of ECT2 (FDR 5.00e-4, cancer/normal ratio 1.88) and suggests over-expression of TNFSF10 (FDR 0.014, cancer/normal ratio 1.78)." (PMID 19419571, 2009).
cancer (continued). "Finally, TAK-981 induced the expression of TNFSF10, encoding for TRAIL, in NK cells and a subsequent increase of TRAIL at their surface, which binds to its receptors (DR4 and DR5) on the surface of cancer cells to induce their apoptosis." (PMID 40661051, 2026). "Subsequently, consider the value of most significantly expression in single-cell samples of PAAD cancer tissues, we labeled the expression levels and expression distribution of RARRES3 and TNFSF10 in the clustered UMAP cell cluster descending plots of cancer and para-cancer tissues." (PMID 38375157, 2024). "Besides, previous studies have shown that TNFSF10 can induce autophagy through the MAPK8 activation pathway of TRAF2 and RIPK1, which in turn blunts the apoptosis of cancer cells." (PMID 38375157, 2024). "Additionally, the average expression of TNF-related genes, including TNFRSF1A, TNFRSF1B, TNFSF10, and TNFRSF21, was higher than that of most other necroptosis genes in pan-cancer." (PMID 37000317, 2023). "TNFSF10 expression on a large cohort of CRC patients was found to be significantly lower in the cancer group compared to the control group and non-significantly lower in metastatic and KRAS-positive group." (PMID 37869102, 2023). "Recent studies found the negative relationship between serum TNFSF10 and clinical outcomes in diseases of non-cancers." (PMID 34356656, 2021). "Moreover, in the results of miR-581 target genes, TNFSF10, HMGA2, CEACAM1, and mTOR have been reported to be involved in proliferation and apoptosis in a number of cancers." (PMID 32899503, 2020). "Tumor necrosis factor-related apoptosis inducing ligand (TRAIL, also called Apo2L or TNFSF10) is capable of inducing apoptosis in cancer cells but not in normal cells." (PMID 17996095, 2007). "To evaluate whether the prognostic value of the CCL22 and TNFSF10 score was independent of known clinical variables, we assessed the biomarker in different clinical cohorts, stratified by gender and cancer type." (PMID 41295982, 2026). "Notably, the GZMA CD4 T cell subset exhibited elevated expression of genes associated with effector and cytolytic functions in CD4 T cells, including GZMA, GZMH, GZMM, and PRDM1, while also showing moderate expression of anti-cancer-related genes such as IFNG, PRF1, and TNFSF10." (PMID 40959273, 2025). "However, despite extensive research on PRICKLE3, TNFSF10, ACSL1 and EP300 in relation to cancer, immunity, and metastasis, their precise involvement in primary resistance mechanisms in SCLC remains unclear and requires further study." (PMID 38957470, 2024). "Finally, TNFSF10—TNFRSF10B (TRIAL—TRIAL-R), SIRPA—CD47 (“don't eat me”), C5AR1—RPS19, and GAS6—AXL act as negative regulators of the innate immune system by inhibiting cytokine responses, phagocytosis of cancer cells, and promoting the immunosuppressive TME." (PMID 37823774, 2023). "Tumor necrosis factor-related apoptosis-inducing ligand (TRAIL, other names: TNFSF10; CD253; Apo-2L; TNLG6A), is a protein belonging to the TNF-superfamily and has been shown in in vitro and in vivo models to induce apoptosis of various types of cancer cells while sparing normal ones." (PMID 30446013, 2018). "TNFSF10, also known as TRAIL or Apo-2 ligand, is a member of the TNF superfamily, and since its discovery it has been used as an antitumour protein because of its ability to induce apoptosis in a variety of human cancer cell lines while leaving normal cells unaffected." (PMID 20588276, 2010). "In addition, many pro-apoptotic factors were lowly expressed, including those expressed at low levels in human HCC, such as TNFSF10, which induces apoptosis in cancer but not normal cells, and STAT1, which mediates the growth inhibition and apoptotic activities of IFN-γ." (PMID 28969016, 2017).
infection (195 papers, 2004 to 2026). The state of being infected such as from the introduction of a foreign agent such as serum, vaccine, antigenic substance or organism. "IFI44, ISG15, MX1, RSAD2, SAMD9 and TNFSF10 were chosen as they are infection-associated genes that show lower expression levels in Holstein infected cells compared to Sahiwal cells." (PMID 35061738, 2022). "Pulmonary arterial endothelial cells responded most rapidly to infection, with high expression of Cxcl10, Tnfsf10, and Ccl7 by 2 dpi." (PMID 34381043, 2021). "We found that the expression of eight genes, including Il18, Il36b, Il17rc, Tnfsf10, Tnfsf11, Tnfsf14, Tnfsf15, and Il1a, were closely correlated with the severity of HAdV-55 infection." (PMID 30787914, 2019). "Tnfsf10 (TRAIL gene), Casp3 and Casp7 were significantly upregulated by infection." (PMID 40547518, 2025). "Significant upregulations could be observed for the genes TNFSF10 (3.8-fold change to WT infection), TNFRSF14 (3.2-fold) and MYD88 (1.9-fold)." (PMID 38400065, 2024). "Upregulation of genes such as CXCL8 (platelet cytokine) and TNFSF10 (apoptosis mediator) in HVR at an early stage of infection might act as pointers of a severe disease course." (PMID 37644081, 2023). "Notably, in unexposed hAECs, TNFSF10/TRAIL was basally expressed in goblet and secretory cells; however, following infection its expression was upregulated in most cell types in WT and NS1R38A virus-infected hAECs." (PMID 36268025, 2022). "These included chemokine ligand IP-10 and genes controlled by pro-inflammatory cytokines TNF-α, IL-1β, IFN-γ; namely, interferon regulatory factor 1, Cd274 antigen, metallothionein 2, proteasome subunit (Psmb9), and tumor necrosis factor Tnfsf10 were progressively up-regulated after infection." (PMID 20082697, 2010). "Therefore, up-regulated TNFSF10 in the mutant infection could only be another factor contributing to the attenuation." (PMID 37513744, 2023). "Among these proteins, in particular, TLR3 activated MSCs secreted TNFSF10, CXCL10, ISG15 and C2 (green highlight, 7C) were found upstream of several affected immune response and infection pathways in all 3 cell types." (PMID 40861855, 2025). "The differentially expressed cytokines such as IL6, IL10, IL11, IL15, TNFSF10, TNFRSF6B and TNFAIP6 were detected in the lung of goats after Pm infection in this study." (PMID 35739866, 2022). "Differential changes in the expression of CCL19, CCL20, IL-8, IL-15, and Trail/TNF (ligand) superfamily members TNFSF10 and TNFSF15 in DT40 cells were also observed at different time points after vvIBDV infection." (PMID 28086922, 2017). "At 6 h post-infection this trend continued, and several other members of the TNF-α superfamily were also up-regulated: TNFSF9, TNFSF10 and TNFSF15 (all at least 1.7-fold higher in H5N1-treated cells)." (PMID 20011590, 2009). "However, despite the absence of IFN-β expression induction in mel Ibr and mel Z, this cell line, in turn, induced the expression of certain ISGs—MxA, TNFSF10, IFIT2 24—72 h post infection." (PMID 32033013, 2020). "Amongst cytokines, the genes for Cxcl9, Cxcl10, Cxcl13, Il-1β, Il-6, Tnf, Tnfsf10, IFN-γ, Ccl2, Ccl4, Ccl7, Ccl17, and Mif were highly up-regulated (ranging from 2- to 405-fold, p ≤ 0.05), whereas Cxcl12 and Cxcl14 were down-regulated during in vivo infection." (PMID 30857242, 2019). "Our RT-qPCR results showed that infection of GSWW, FL-12 or VR2332 could induce TNFSF10 expression." (PMID 28694521, 2017).
bacterial infections (21 papers, 2015 to 2025). "These were predominantly enriched in the Toll-like receptor signaling pathway and bacterial infection-related genes, such as TLR4, JUN, and TNFSF10." (PMID 41375527, 2025). "The leading edge genes driving the enrichment of the inflammatory response pathway in response to bacterial infections included several relevant for T‐cell activation (IL1B, CCL5, TNFSF10, GPR183, CD69, SELL), suggesting that cDC2s were undergoing conventional maturation." (PMID 34333764, 2022).
hematological malignancies (14 papers, 2013 to 2025). "The most significantly hypermethylated CpGs were frequently linked to genes involved in the pathogenesis of hematological diseases, including RUNX1, BRD4, SRSF2, SETBP1 and TNFSF10." (PMID 40319310, 2025).
inflammation (7 papers, 2014 to 2024). Aberrant reaction of the microcirculation characterized by movement of fluid and leukocytes from the blood into extravascular tissues. "TNFSF10, also named TRAIL, mediates autoimmune inflammation and cellular homeostasis by transmitting apoptotic signals to induce apoptosis and was found to suppress autoimmune colitis by inhibiting colonic T-cell activation." (PMID 36145301, 2022).
neurological diseases (7 papers, 2016 to 2025). "TNFSF10, also known as TRAIL, is a key molecule in neurological diseases." (PMID 41021615, 2025).